APP (amyloid beta precursor protein)
Description:
Functions as a cell surface receptor and performs physiological functions on the surface of neurons relevant to neurite growth, neuronal adhesion and axonogenesis. Interaction between APP molecules on neighboring cells promotes synaptogenesis. Involved in cell mobility and transcription regulation through protein-protein interactions. Can promote transcription activation through binding to APBB1-KAT5 and inhibits Notch signaling through interaction with Numb. Couples to apoptosis-inducing pathways such as those mediated by G(o) and JIP. Inhibits G(o) alpha ATPase activity (By similarity). Acts as a kinesin I membrane receptor, mediating the axonal transport of beta-secretase and presenilin 1 (By similarity). By acting as a kinesin I membrane receptor, plays a role in axonal anterograde transport of cargo towards synapses in axons. Involved in copper homeostasis/oxidative stress through copper ion reduction. In vitro, copper-metallated APP induces neuronal death directly or is potentiated through Cu(2+)-mediated low-density lipoprotein oxidation. Can regulate neurite outgrowth through binding to components of the extracellular matrix such as heparin and collagen I and IV. The splice isoforms that contain the BPTI domain possess protease inhibitor activity. Induces a AGER-dependent pathway that involves activation of p38 MAPK, resulting in internalization of amyloid-beta peptide and leading to mitochondrial dysfunction in cultured cortical neurons. Provides Cu(2+) ions for GPC1 which are required for release of nitric oxide (NO) and subsequent degradation of the heparan sulfate chains on GPC1. Amyloid-beta peptides are lipophilic metal chelators with metal-reducing activity. Bind transient metals such as copper, zinc and iron. In vitro, can reduce Cu(2+) and Fe(3+) to Cu(+) and Fe(2+), respectively. Amyloid-beta peptides bind to lipoproteins and apolipoproteins E and J in the CSF and to HDL particles in plasma, inhibiting metal-catalyzed oxidation of lipoproteins. Promotes both tau aggregation and TPK II-mediated phosphorylation. Interaction with overexpressed HADH2 leads to oxidative stress and neurotoxicity. Also binds GPC1 in lipid rafts. [Amyloid-beta protein 42]: More effective reductant than amyloid-beta protein 40. May activate mononuclear phagocytes in the brain and elicit inflammatory responses. Appicans elicit adhesion of neural cells to the extracellular matrix and may regulate neurite outgrowth in the brain. The gamma-CTF peptides as well as the caspase-cleaved peptides, including C31, are potent enhancers of neuronal apoptosis.
Synonyms: CVAP; PN-II; AD1; alpha-sAPP; AAA; ABETA; ABPP; APPI; CTFgamma; PN2; preA4
Tractability: Small molecule: a drug acting on it is in phase 2 or 3 trials; a structure with a bound ligand is known; a high-quality ligand is known; it has a high-quality binding pocket; it belongs to a druggable protein family. Antibody: an approved drug acts on it; UniProt places it where antibodies can reach, with high confidence; its Gene Ontology location is reachable by antibodies, with high confidence; UniProt predicts a signal peptide or a membrane-spanning region. PROTAC: UniProt records ubiquitination sites on it; ubiquitination databases record sites on it; a small molecule that binds it is known. Other modalities: a drug acting on it is in phase 2 or 3 trials.
Target class: Membrane receptor
Gene: Protein-coding gene on chromosome 21 (25,880,535 to 26,171,128, reverse strand). Ensembl gene ENSG00000142192.
Subcellular location: Cell membrane; Membrane; Perikaryon; Cell projection, growth cone; Membrane, clathrin-coated pit; Early endosome; Cytoplasmic vesicle; Endoplasmic reticulum (C83); Golgi apparatus; Early endosome (C99); Secreted (Soluble APP-beta); Cell surface (Amyloid-beta protein 40); Cell surface (Amyloid-beta protein 42); Nucleus (Gamma-secretase C-terminal fragment 59); Cytoplasm
Subcellular location (Human Protein Atlas): Golgi apparatus; Vesicles; Predicted to be secreted
Pathways (Reactome):
Disease: Aggregated β-amyloid induces FXII autocatalysis; Aggregated β-amyloid interacts with fibrinogen; Deregulated CDK5 triggers multiple neurodegenerative pathways in Alzheimer's disease models; Purinergic signaling in leishmaniasis infection
Immune System: Advanced glycosylation endproduct receptor signaling; TAK1-dependent IKK and NF-kappa-B activation; TRAF6 mediated NF-kB activation; The NLRP3 inflammasome
Metabolism of proteins: Amyloid fiber formation; Mitochondrial protein degradation; Post-translational protein phosphorylation; Regulation of Insulin-like Growth Factor (IGF) transport and uptake by Insulin-like Growth Factor Binding Proteins (IGFBPs)
Signal Transduction: Formyl peptide receptors bind formyl peptides and many other ligands; G alpha (i) signalling events; G alpha (q) signalling events
Hemostasis: Platelet degranulation; Regulation of clotting cascade
Extracellular matrix organization: ECM proteoglycans
Protein localization: Insertion of tail-anchored proteins into the endoplasmic reticulum membrane
Vesicle-mediated transport: Lysosome Vesicle Biogenesis
Gene Ontology:
Molecular function: enzyme binding; identical protein binding; protein binding; protein serine/threonine kinase binding; PTB domain binding; receptor ligand activity; serine-type endopeptidase inhibitor activity; signaling receptor binding; DNA binding; signaling receptor activator activity; growth factor receptor binding; heparin binding; molecular function activator activity; peptidase activator activity; transition metal ion binding
Biological process: amyloid fibril formation; astrocyte activation; astrocyte activation involved in immune response; cellular response to amyloid-beta; learning; learning or memory; microglia development; microglial cell activation; modulation of excitatory postsynaptic potential; negative regulation of cell population proliferation; negative regulation of gene expression; negative regulation of long-term synaptic potentiation; neuron projection maintenance; positive regulation of amyloid fibril formation; positive regulation of calcium-mediated signaling; positive regulation of chemokine production; positive regulation of ERK1 and ERK2 cascade; positive regulation of gene expression; positive regulation of glycolytic process; positive regulation of inflammatory response; positive regulation of interleukin-1 beta production; positive regulation of interleukin-6 production; positive regulation of JNK cascade; positive regulation of long-term synaptic potentiation; positive regulation of non-canonical NF-kappaB signal transduction; and 47 more
Cellular component: amyloid-beta complex; cell surface; cytoplasm; cytoplasmic vesicle; dendrite; dendritic shaft; dendritic spine; early endosome; early endosome membrane; endoplasmic reticulum; endosome; extracellular exosome; extracellular region; Golgi apparatus; membrane; membrane raft; nuclear envelope lumen; nucleus; perikaryon; perinuclear region of cytoplasm; plasma membrane; receptor complex; synapse; axon; cytosol; and 18 more
Genetic constraint (gnomAD): Loss-of-function variants: 30 observed, 99.16 expected, observed/expected ratio (o/e) 0.3, 90% interval 0.22 to 0.41. The upper end of that interval is the gene's LOEUF score, 0.41, which puts it in group 1 of 6, group 1 being the genes least tolerant of losing a copy. Missense variants: 827 observed, 1,025.5 expected, observed/expected ratio (o/e) 0.81, 90% interval 0.76 to 0.85. Synonymous variants: 358 observed, 372.08 expected, observed/expected ratio (o/e) 0.96, 90% interval 0.88 to 1.05.
Gene-disease validity (ClinGen):
ClinGen rates the evidence that APP causes each of these diseases.
cerebral amyloid angiopathy, APP-related (autosomal dominant): Definitive.
Homologues: Orthologues: macaque APP (97% identical), guinea pig APP (97% identical), rabbit APP (97% identical), dog APP (97% identical), rat App (97% identical), chimpanzee APP (96% identical), pig APP (95% identical), mouse App (95% identical), tropical clawed frog app (85% identical), zebrafish appb (61% identical), Drosophila melanogaster Appl (28% identical), Caenorhabditis elegans apl-1 (26% identical), and 1 more. Paralogues in human: APLP2 (49% identical), APLP1 (31% identical).
Diseases named in the same sentence as APP in open-access papers:
APP is named in the same sentence as 485 diseases in open-access papers, as found by Europe PMC text mining. Sharing a sentence is not in itself a finding about the gene and the disease. The quoted sentences say what the papers report.
Alzheimer disease (3,110 papers, 2000 to 2026). A progressive, neurodegenerative disease characterized by loss of function and death of nerve cells in several areas of the brain leading to loss of cognitive function such as memory and language. "Dyrk1A activity is responsible for neurological defects in Down syndrome and acts as a priming kinase for Alzheimer's disease-associated proteins Tau and APP." (PMID 42131436, 2026). "NRBF2 is also linked to Alzheimer disease (AD) as it mediates autophagic degradation of amyloid beta precursor protein (APP) and its protein level is reduced in brains of 5xFAD transgenic AD mice." (PMID 41162841, 2026). "One of the main pathological features of Alzheimer's disease (AD) is the accumulation of amyloid β (Aβ) peptides, which is encoded by the amyloid precursor protein (APP) gene." (PMID 41624195, 2026). "The APPSAA mouse model (containing the humanized APP with three familial Alzheimer’s disease mutations) and the APPWT control (containing wildtype humanized APP) are the first commercially available APP KI mice within the United States." (PMID 39920176, 2025). "It has been reported that DS individuals are more susceptible to Alzheimer’s disease as the gene encoding amyloid precursor protein, APP, is located on chromosome 21." (PMID 40155863, 2025). "Several of these mutations are disease-associated, similar to the Alzheimer’s disease-causing APP London (V717I) mutation." (PMID 40593564, 2025). "Chromosomal abnormalities, such as trisomy 21 in Down syndrome, significantly increase the risk of Alzheimer's disease due to overexpression of the APP gene, leading to early β-amyloid accumulation and accelerated neurodegeneration." (PMID 41179085, 2025). "APLP1 and APLP2 demonstrate homology to APP in sequence and domain architecture, though only APP has the specific amyloid-β sequence associated with Alzheimer’s disease." (PMID 40265027, 2025). "One of the first organoid models for Alzheimer’s disease was generated from mutated progenitor cells containing familial AD (fAD) mutations in the APP and PSEN1 genes, resulting in organoids presenting amyloid aggregation and hyperphosphorylated tau." (PMID 40244116, 2025). "Alzheimer's disease (AD) is characterized by the deposition of intraneuronal hyperphosphorylated tau protein and aggregation of extracellular misprocessed amyloid precursor protein (APP), which leads to neuronal loss and dementia." (PMID 41142012, 2025). "Down syndrome increases the risk of Alzheimer’s disease due to the triplication of chromosome 21, which contains the APP (amyloid precursor protein) gene." (PMID 40896041, 2025). "ADAD accounts for approximately 1% of Alzheimer’s disease (AD) cases and is caused by autosomal dominant mutations in the Amyloid Beta Precursor Protein (APP), Presenilin 1 (PSEN1), or Presenilin 2 (PSEN2) genes." (PMID 39828719, 2025). "Calculated concentration (nM) of each Aβ variant resulting from processing APP substrate by wild-type (WT) vs. familial Alzheimer’s disease (FAD)-mutant γ-secretase*." (PMID 39932776, 2025). "APP and amyloid-β have been observed in the mitochondria and in the Mitochondria-Associated-Membrane in Alzheimer’s disease patient’s brain, [for review see]." (PMID 40302938, 2025). "For example, an inversion affecting APP, a gene implicated in Alzheimer’s disease, was initially reported by Manta as ambiguous BND events." (PMID 41169152, 2025). "Alzheimer's disease (AD) begins with intermolecular association of Aβ, a 40- to 42-amino acid peptide derived from proteolytic cleavage of the amyloid precursor protein (APP)." (PMID 39955064, 2025). "There is evidence that intraneural accumulation of the processed products of APP, together with phosphorylated tau, affects synaptic function leading to the cognitive defects associated with Alzheimer’s disease [for reviews]." (PMID 40302938, 2025).
Alzheimer disease (continued). "Amyloid precursor protein (APP), implicated in Alzheimer's disease, has an E2 domain that binds copper ions with a dissociation constant of KD ∼ 10−12 M and is proposed to be involved in iron homeostasis, copper trafficking, and oxidative stress response." (PMID 39670805, 2025). "This isoform switch towards APP695 in iCN is consistent with previous findings in Alzheimer’s disease brains, where significant transcript-level changes in APP were identified and linked to disease-relevant processing pathways." (PMID 40735840, 2025). "Familial Alzheimer’s disease (FAD) is frequently associated with mutations in the amyloid precursor protein (APP), which are thought to lead to cognitive deficits by impairing NMDA receptor (NMDAR)-dependent forms of synaptic plasticity." (PMID 39732167, 2025). "Familial early-onset Alzheimer's disease (EOAD) is a rare form of dementia often caused by autosomal dominant mutations in APP, PSEN1, or PSEN2." (PMID 40575115, 2025). "Among these DEGs, certain genes associated with Alzheimer’s disease were identified, including Amyloid Beta Precursor Protein (APP), Presenilin 1 (PSEN1), and Cathepsin D (CTSD)." (PMID 40243634, 2025). "APP, the aggregation of which causes Alzheimer’s disease, is also a receptor for SLIT, mediating neural circuit formation via axon guidance." (PMID 41465490, 2025). "Mutations that lead to the development of early-onset Alzheimer’s disease are found within the APP (amyloid precursor protein), PSEN1 (presenilin 1), and PSEN2 (presenilin 2) genes, the products of which regulate the production of Aβ." (PMID 40869138, 2025). "The Icelandic mutation in the amyloid precursor protein (APP), APPA673T, has been identified in Icelandic and Scandinavian populations and is associated with a significantly lower risk of developing Alzheimer's disease (AD)." (PMID 41594570, 2025). "It has been linked to Alzheimer’s disease through a proposed role in regulating amyloid precursor protein (APP) internalization and processing, thereby affecting amyloid-β generation and accumulation." (PMID 40863490, 2025). "In this study, we compared brain tissues extracted from 32-week-old male wild-type mice and 5×FAD transgenic Alzheimer's disease model mice, which carry mutations in the amyloid precursor protein ( APP ) and presenilin 1 ( PS1 ) genes." (PMID 40150820, 2025). "Our analysis of FAD mutations in PSEN1, PSEN2, and APP has focused exclusively on neurons, a key brain cell type affected in Alzheimer’s disease." (PMID 39754192, 2025). "The 5xFAD mice overexpress the human amyloid precursor protein (APP) containing three familial Alzheimer's disease (FAD) mutations, and human presenilin‐1 (PSEN1) with two additional FAD mutations." (PMID 41047765, 2025). "APP is primarily known for its role in the generation of amyloid-beta peptides associated with Alzheimer’s disease (AD)." (PMID 40993824, 2025). "This cellular model can be used to study disease mechanisms, for example, by expressing a central gene implicated in Alzheimer’s disease, such as the wild-type or mutant form of amyloid precursor protein (APP)." (PMID 40869348, 2025). "The presence of aberrant forms of amyloid precursor protein (APP) is linked to Alzheimer disease, but its loss leads to motor deficits." (PMID 41284713, 2025). "Given the location of APP on chromosome 21, we evaluated the expression of genes associated with Alzheimer’s disease." (PMID 41002374, 2025). "Consumption of a 42–60% HFD increases brain beta-amyloid (Aβ) deposition levels, a hallmark of Alzheimer's disease (AD), and contributes to gliosis in APP/PS1 mice; however, these changes likely depend on the time frame of HFD consumption." (PMID 40775599, 2025). "The 5XFAD mouse is a well-characterized and aggressive model of early-onset Alzheimer’s disease, engineered to overexpress human APP and PSEN1 mutations associated with familial AD." (PMID 40313736, 2025).